PLEC (plectin)
Diseases named in the same sentence as PLEC in open-access papers (continued):
Sharing a sentence is not in itself a finding about the gene and the disease.
prostate carcinoma (10 papers, 2013 to 2025). A carcinoma that arises from epithelial cells of the prostate gland. "In PTEN-negative prostate cancer cells, the disassembly of HDs leads to the association of plectin with actin-rich focal adhesions, which results in the activation of the EGFR/PI3K/Akt and FAK/Src pathways to promote tumor progression." (PMID 39334817, 2024). "Furthermore, its high expression is associated with poor prognosis in a variety of human cancers.Thus, overexpression of plectin might contribute to cell migration and invasion in prostate cancer cells through its association with integrin β4." (PMID 23717685, 2013). "Integrin-linked kinase (ILK), plectin (PLEC), paxillin (PXN), talin 1 (TLN1), and vinculin (VCL) are other adhesome proteins that were implicated in prostate cancer and that showed biomarker potential in this cancer type." (PMID 38255186, 2023). "The PTEN-deficient status is critical because disruption of HDs (α6-KO or β4-KO) in prostate cancer cells with intact PTEN led to robust downregulation of plectin." (PMID 35773413, 2022). "We discuss an emerging scenario where hemidesmosomal α6β4-integrins and plectin function as tumor suppressors but adopt new oncogenic roles upon hemidesmosome disassembly in prostate cancer." (PMID 36612146, 2022). "In this review, we elaborate on the current knowledge of the kinase signaling pathways regulated by α6β4-integrins and plectin in the context of prostate cancer." (PMID 36612146, 2022). "In prostate cancer, IHC analysis demonstrated significantly higher plectin staining in prostate cancer tissues and lymph node metastases when compared to patient-matched benign prostate tissue and cancer-free lymph node tissues, respectively." (PMID 34571895, 2021). "We therefore conclude that a reduction in the levels of both plectin and vimentin produced by the cells resulted in suppressed cell invasion in the prostate cancer cell line." (PMID 23717685, 2013). "The differentially regulated proteins identified in the study, including plectin and vimentin, are discussed in the context of their significance to prostate cancer progression." (PMID 23717685, 2013). "Proteomic analysis suggested that plectin regulates extracellular matrix, laminin, amino acid metabolism, cytoskeletal proteins, and cellular stress response, positioning it as a critical regulator of prostate cancer growth and metastasis." (PMID 39334817, 2024). "Moreover, in PTEN-negative prostate cancer cells, plectin binds to actin-rich adhesions, leading to the activation of epidermal growth factor receptor (EGFR)/phosphoinositide 3-kinase (PI3K)/protein kinase B (PKB) and focal adhesion kinase (FAK)/Src pathways." (PMID 39334817, 2024). "Finally, a recent study suggested that hemidesmosomal α6β4 integrins and plectin are tumor suppressors in prostate cancer but become oncogenic upon hemidesmosome disassembly." (PMID 38255186, 2023). "In vitro, plectin-knockdown prostate cancer cells demonstrate decreased migration and invasion." (PMID 34571895, 2021). "Similarly, in prostate cancer, plectin-knockdown cells showed decreased cell growth in vitro and inhibited tumor growth in vivo." (PMID 34571895, 2021). "In summary, we have identified several proteins including plectin and vimentin that may act as markers for prostate cancer disease progression." (PMID 23717685, 2013). "We examined whether plectin and vimentin contribute to cell proliferation in prostate cancer using the RNAi technique." (PMID 23717685, 2013). "To determine whether plectin and vimentin are involved invasion and migration and thus potentially prostate cancer metastasis, we transfected PC3-ML2 with siRNA targeting the two genes." (PMID 23717685, 2013). "It is noteworthy that plectin-dependent effects on PI3K/Akt and FAK/Erk signaling were recently described for prostate cancer and head and neck squamous carcinoma cells, indicating that these observations have broader implications beyond liver cancer." (PMID 40052672, 2025).
prostate carcinoma (continued). "Proteomic comparison of the prostate cancer cell line PC3 and a metastatic derivative PC3 cell line demonstrated a robust increase in the abundance of plectin and vimentin, a key EMT marker, in the more aggressive line." (PMID 34571895, 2021). "In prostate cancer, relative to benign tissues, plectin expression is increased in both primary tumors and lymph node metastases, indicating a potential role in metastatic progression." (PMID 41011568, 2025). "This is further supported by the lack of plectin expression in the benign non-tumorigenic epithelial RWPE-1 prostate cancer cell line." (PMID 23717685, 2013). "An early report suggested that prostate carcinoma cells lacked hemidesmosomal proteins, the integrin α6β4, BP180, LAMC2, and collagen VII, but did express BP230, plectin, and the integrin laminin receptors α3β1 and α6β1." (PMID 38255186, 2023).
colon carcinoma (8 papers, 2018 to 2026). "In head and neck squamous cancer cells and colon cancer cells, plectin promoted the migration and invasion of these cells through the activation of ERK1/2." (PMID 36613521, 2022). "Plectin expression was significantly higher in the SW480 colon cancer cell line than the lower grade HT29 colon cancer cell line." (PMID 34001250, 2021). "In colon cancer, plectin expression was significantly increased in higher-grade SW480 cells than lower-grade HT29 cells." (PMID 34571895, 2021). "Suppression of plectin inhibited adhesion, migration, and invasion of colon carcinoma cells." (PMID 36185199, 2022). "Similarly, plectin mRNA expression was significantly lower in colon carcinoma compared to normal tissue, while previous plectin IHC analysis demonstrated abundant expression in malignant tissue." (PMID 34571895, 2021). "Moreover, plectin targeting with plecstatin-1 reduced tumor growth in B16 melanoma and CT-26 colon tumor mouse models." (PMID 34571895, 2021). "On the one hand, plectin expression obviously increases in some types of tumors and promotes tumor progression, such as HNSCC, OSCC, colon cancer, ESCC, and so on." (PMID 39334817, 2024). "Using human colon cancer cell line SW480-ADH, treatment with a vitamin D metabolite, 1α,25(OH)2D3, increased plectin expression, inhibited cell proliferation, and induced epithelial differentiation." (PMID 34571895, 2021). "The suppression of plectin inhibits cell migration and invasion in both HNSCC and colon carcinoma cells." (PMID 29587367, 2018). "High levels of plectin have also been observed in HNSCC, colon carcinoma cells, and high-metastatic bladder cancer cells, showing promotion effects on cancer cell migration, invasion, and metastasis." (PMID 29587367, 2018). "In HNSCC, plectin has been shown to promote the migration and invasion of HNSCC cells through activation of ERK1/2, while in colon carcinoma cells plectin is targeted to podosome-like adhesions to regulate cell migration and invasion in an isoform-specific manner." (PMID 29587367, 2018). "Moreover, plectin expression is upregulated in SW480 colon cancer cells, and silencing plectin weakens the migration, invasion, and adhesive capabilities of SW480 cells, implying that plectin participates in actin assembly and invasion in colorectal cancer development processes." (PMID 39334817, 2024).
Alexander disease (6 papers, 2015 to 2024). Alexander disease (AxD) is a rare neurodegenerative disorder of the astrocytes comprised of two clinical forms: AxD Type I and Type II manifesting with various degrees of macrocephaly, spasticity, ataxia and seizures and leading to psychomotor regression and death. "Some parallels can be drawn from the involvement of plectin in Alexander disease, a rare progressive neurodegenerative disorder caused by dominantly acting mutations in GFAP." (PMID 32630739, 2020). "Plectin has been linked to epilepsy and Alexander disease, a rare demyelinating disease." (PMID 38438384, 2024). "The overexpression of plectin cDNA converted these aggregates to networks composed of thin filaments, whereas the expression of GFAP with the most common Alexander disease mutation lowered plectin levels." (PMID 32630739, 2020). "Similar to increased plectin levels in Alexander disease patients, we found increased Shot expression in Alexander disease model flies compared to controls." (PMID 29765022, 2018). "Astrocytic GFAP expression is associated with aging and AD; dominant GFAP mutations in Alexander disease cause protein aggregates that contain GFAP, vimentin, plectin, ubiquitin, and small chaperones such as α‐crystallin." (PMID 27448508, 2016). "Several of the most enriched proteins (plectin, glial fibrillar acidic protein, vimentin, Hsp 27, and ubiquitin) are known to form complex astrocytic inclusions, so-called Rosenthal fibers, in the neurodegenerative disorder Alexander disease." (PMID 24798087, 2015). "For example, in Alexander disease (AxD), a rare and usually fatal neurodegenerative disorder that is associated with GFAP mutations, plectin in astrocytes accumulates in protein aggregates called Rosenthal fibres (RFs)." (PMID 34572001, 2021). "Interestingly, some of the BMAA-induced enriched proteins in the histopathologically altered area, such as plectin, GFAP, vimentin, Hsp 27, and ubiquitin, are known to form complex astrocytic inclusions, the so-called Rosenthal fibers, in the neurodegenerative disorder Alexander disease." (PMID 24798087, 2015).
cardiomyopathy (6 papers, 2016 to 2024). A disease of the heart muscle or myocardium proper. "It is caused by compound heterozygous or homozygous PLEC variants, and research on these conditions has led to observations that implicated it in various forms of cardiomyopathy other than ARVC." (PMID 30161220, 2018). "We therefore cannot exclude that some identified PLEC variants may have an effect on the development of ARVC or another type of cardiomyopathy." (PMID 30161220, 2018). "Data analysis also indicated that there are many genes related to cardiomyopathy, such as TTN, NEFH, PLEC, CASQ2, and SYNE1." (PMID 33200202, 2020).
atrial fibrillation (5 papers, 2018 to 2024). A disorder characterized by an electrocardiographic finding of a supraventricular arrhythmia characterized by the replacement of consistent P waves by rapid oscillations or fibrillatory waves that vary in size, shape and timing and are accompanied by an irregular ventricular response. "An Icelandic study showed that the missense mutation of PLEC in the heart of local people was related to atrial fibrillation." (PMID 38149679, 2024). "A genome-wide association study performed with 14,225 subjects with atrial fibrillation and 374,939 control subjects from the Icelandic population, identified a plectin sequence variant (rs373243633) corresponding to pG3988S, as a moderate risk factor for atrial fibrillation." (PMID 34572100, 2021). "We prioritised rs11786896, which colocalised with Alzheimer’s disease, atrial fibrillation and expression of PLEC in the heart left ventricle, and rs7529220, which colocalised with Alzheimer’s disease, atrial fibrillation and expression of C1Q family genes." (PMID 39537608, 2024). "Like p.Gln254Pro in MYZAP, the three low-frequency missense and frameshift variants we have previously reported to increase the risk of atrial fibrillation, in MYH6, MYL4, and PLEC, also increase the risk of SSS8." (PMID 30271950, 2018).
colorectal cancer (5 papers, 2021 to 2025). A primary or metastatic malignant neoplasm that affects the colon or rectum. "Similarly, analysis of samples from colorectal cancer patients demonstrated a heightened plectin expression in adenocarcinomas and locally invasive nests relative to normal tissues." (PMID 39334817, 2024). "Subsequent validation in HCT116 cells confirmed a strong interaction between Rap2B and plectin, which was further corroborated by the co-immunoprecipitation between endogenous Rap2B and plectin in U2OS osteosarcoma cells and LOVO colorectal cancer cells." (PMID 40223002, 2025).
limb-girdle muscular dystrophy (5 papers, 2011 to 2023). Limb-girdle muscular dystrophy (LGMD) is a heterogeneous group of muscular dystrophies characterized by proximal weakness affecting the pelvic and shoulder girdles. "Mutations in plectin have been associated with diseases such as epidermolysis bullosa simplex with muscular dystrophy and limb-girdle muscular dystrophy (LGMD)." (PMID 30357519, 2019). "Another dramatic example is a recently discovered mutation in plectin exon 1f that results in Limb-Girdle muscular dystrophy without skin involvement." (PMID 22144912, 2011).
lung carcinoma (5 papers, 2014 to 2024). "More detailed studies in lung cancer patients with different histology, gender and smoking status showed that the high plectin expression is associated with poor survival with the only exception of patient with squamous carcinoma." (PMID 31628412, 2019). "They validated pancreatic, ovarian, and lung cancer tissue as having strong plectin membrane staining, consistent with their CSP-positive status." (PMID 34571895, 2021). "It is interesting that the decrease of plectin associated lung cancer survival is more significant in non-smokers (HR = 3.2, p = 2.8e−5) than that in smokers (HR = 1.9, p = 4.8e−4)." (PMID 31628412, 2019). "Higher expression of plectin is strongly associated with poor survival in patients with adenocarcinoma (HR = 2.2, P = 5.5e−11) and in never smoking lung cancer patients (HR = 3.2, P = 2.8e−5)." (PMID 31628412, 2019). "Plectin has been reported to be a biomarker that is frequently overexpressed in some cancer types, including PAAD, lung cancer, and head and neck cancers." (PMID 39152432, 2024). "The down regulation of plectin gene PLEC1 by siRNA promotes the migration and invasion of the A549 lung cancer cells." (PMID 25566531, 2014). "Besides the prevention of plectin siRNA, curcumin demonstrated its ability to inhibit the matrix metalloproteinase (MMP)-2 and 9 as well as VEGF in human lung cancer A549 cells in vitro." (PMID 25566531, 2014). "Studying the function of plectin may give important insight in the study of non-smoking related lung cancer." (PMID 31628412, 2019).
melanoma (5 papers, 2022 to 2025). A malignant, usually aggressive tumor composed of atypical, neoplastic melanocytes. "Since Src activity is reduced in plectin-deficient melanomas, we examined the relationship between plectin and Src signaling." (PMID 36038818, 2022). "To determine whether these observations were cell-type specific, we also generated plectin deficient human HMV-II human melanoma cells by shRNA mediated knockdown." (PMID 36038818, 2022). "In plectin-deficient melanomas, proliferation and adhesion are impaired." (PMID 36038818, 2022). "Downregulation of plectin reduces tumor mass and attenuates cell proliferation by inhibiting the activity of the Src oncogene in melanoma cells." (PMID 41011568, 2025). "Meanwhile, plectin also exhibits high expression in other tumors such as pancreatic ductal adenocarcinomas (PDACs), melanoma, bladder cancer, ovarian cancer, and endometrial cancer, indicating its tumorigenic role." (PMID 39334817, 2024). "In melanoma, inhibition of plectin leads to the formation of low-density tumors, affecting tumor cell proliferation and adhesion processes." (PMID 39334817, 2024). "Our present study strongly supports a role for plectin in melanoma during early stage events, such as primary tumor formation." (PMID 36038818, 2022). "Plectin plays a key role in robust tumor formation in melanoma by regulating cell proliferation and aggregation through Src signaling." (PMID 36038818, 2022). "Further studies, especially on invasion and metastasis, are required to clarify the role of plectin in melanoma progression." (PMID 36038818, 2022). "Recently, a novel anti-tumor agent targeting plectin, ruthenium pyridinecarbothioamide, was shown to suppress tumor growth in a B16 melanoma cell model." (PMID 36038818, 2022). "In melanoma cells, the downregulation of plectin activated ERK1/2, which in turn promoted the migration of the cells." (PMID 36613521, 2022). "Analysis of a GEO dataset showed that plectin-and Src-related genes are highly expressed in human primary melanoma in patients compared to human melanocytes." (PMID 36038818, 2022). "In this study, we examined the role of plectin and its interaction with Src signaling in melanoma cells." (PMID 36038818, 2022). "An anti-tumor agent targeting plectin, ruthenium pyridinecarbothioamide, has been recently developed for the treatment of melanoma." (PMID 36038818, 2022). "This suggests that plectin plays an important role in both cell proliferation and in the formation of cell-to-cell or cell-to-matrix adhesion of melanoma cells." (PMID 36038818, 2022). "Overexpression of constitutively activated Src partially rescued the defective proliferation and adhesions suggesting that plectin regulates the proliferation and adhesion of melanoma cells through Src-dependent and Src-independent mechanisms." (PMID 36038818, 2022). "This suggests that the suppression of plectin may promote melanoma after the formation of the primary tumor because the primary tumor had already been formed upon diagnosis." (PMID 36038818, 2022). "The molecular mechanisms by which plectin affects melanoma is still unclear." (PMID 36038818, 2022). "Given that Src activity is reduced in PKO cells, we next sought to determine whether plectin affects melanoma cell behavior via Src signaling." (PMID 36038818, 2022). "In this study, we demonstrated that plectin was essential for Src activation in melanoma cells." (PMID 36038818, 2022). "In this study, we examined the role of plectin in melanoma tumor formation." (PMID 36038818, 2022). "We used CRISPR/Cas9 gene editing to knock-out plectin in B16 mouse melanoma cells." (PMID 36038818, 2022). "Based on our experimental data, plectin may be required for malignancy and primary tumor formation in melanoma." (PMID 36038818, 2022). "Thus, the depletion of plectin impairs Src signaling in melanoma cells." (PMID 36038818, 2022). "We next examined whether plectin also interacts with src in melanoma cells." (PMID 36038818, 2022).
melanoma (continued). "Therefore, the role of plectin in melanoma progression may differ at each phase." (PMID 36038818, 2022). "To examine the role of plectin in melanoma, we used CRISPR/Cas9 gene editing to delete plectin in murine B16 melanoma cells (PKO cells)." (PMID 36038818, 2022). "However, the effects of plectin inhibition during the late stage of melanoma remain unclear." (PMID 36038818, 2022).
Epidermolysis bullosa simplex with muscular dystrophy (4 papers, 2015 to 2024). Epidermolysis bullosa simplex with muscular dystrophy (EBS-MD) is a basal subtype of epidermolysis bullosa simplex (EBS, see this term) characterized by generalized blistering associated with muscular dystrophy. "Most mutations in the human plectin gene (PLEC) on chromosome 8q24 lead to epidermolysis bullosa simplex with muscular dystrophy (EBS-MD, MIM #226670), an autosomal recessive skin blistering disorder associated with progressive muscle weakness." (PMID 37174658, 2023).
limb girdle muscular dystrophy type 2Q (4 papers, 2015 to 2020). "Moreover, PLEC mutations can cause EBS-MD associated with a myasthenic syndrome (EBS-MD-MyS), EBS with pyloric atresia (EBS-PA), EBS-Ogna, or limb-girdle muscular dystrophy type 2Q (LGMD2Q)." (PMID 25447312, 2015). "Mutations in the human plectin gene may result in autosomal recessive EBS-MD, EBS-MD with myasthenic features (EBS-MD-MyS), EBS with pyloric atresia (EBS-PA) limb girdle muscular dystrophy type 2Q (LGMD2Q), skin-only EBS and the autosomal dominant variant EBS-Ogna." (PMID 32630739, 2020).